RNU6-203P (RNA, U6 small nuclear 203, pseudogene)
Gene: Small nuclear RNA gene on chromosome X (133,531,723 to 133,531,826, reverse strand). Ensembl gene ENSG00000206765.
Homologues: Orthologues: chimpanzee U6 (99% identical), macaque U6 (92% identical). Paralogues in human: RNU6-1152P (91% identical), RNU6-41P (91% identical), RNU6-1060P (90% identical), RNU6-15P (90% identical), RNU6-19P (90% identical), RNU6-820P (90% identical), RNU6-12P (89% identical), RNU6-13P (89% identical), RNU6-166P (89% identical), RNU6-211P (89% identical), RNU6-25P (89% identical), RNU6-31P (89% identical), and 1286 more.